FGF9 (fibroblast growth factor 9)
Diseases named in the same sentence as FGF9 in open-access papers (continued):
Sharing a sentence is not in itself a finding about the gene and the disease.
osteosarcoma (1 paper, 2019). A usually aggressive malignant bone-forming mesenchymal neoplasm, predominantly affecting adolescents and young adults. "Thus CDKN2A/B, IGF1 and the two single candidates at their loci – MTMR7, FGF9 – seem likely to be associated with canine osteosarcoma risk." (PMID 30890123, 2019). "The contribution of FGF9 to osteosarcoma risk could also stem from its role in angiogenesis associated with long bone growth and repair; or could be due to altered expression in the hypothalamus, which, in concert with the pituitary, is a master regulator of long bone growth." (PMID 30890123, 2019). "FGF9 has strong relevance to skeletal development and osteosarcoma." (PMID 30890123, 2019).
periodontal disease (1 paper, 2023). "Furthermore, CXCL5, ADM, FGF9, AIMP1, STC1, and CDKN2A might have a significant impact on the development of HNSC caused by periodontal disease." (PMID 37675228, 2023).
prostate (1 paper, 2019). "Overexpression of FGF9 in mouse prostate epithelial cells leads to development of prostate lesions in an expression level- and age-dependent manner." (PMID 30761180, 2019). "Furthermore, overexpression of FGF9 in the TRAMP (transgenic adenocarcinoma of the mouse prostate) PCa model accelerates the development of advanced PCa." (PMID 30761180, 2019).
prostate tumors (1 paper, 2024). "In Pten-deficient prostate tumors with Klf5KR mutant, overactivation of Fgfr1 signaling was further supported by increased Fgf9 secretion and upregulated Cx3cr1 expression." (PMID 38781024, 2024).
respiratory infection (1 paper, 2022). "In the current study, we found that FGF9 overexpression in club cells increased susceptibility to respiratory infection." (PMID 35675358, 2022).
Senile plaques (1 paper, 2017). Senile plaques are extracellular deposits of amyloid in the gray matter of the brain. "Accordingly, FGF-9 immunoreactivity has been detected in human hippocampal and cortical neurons, astrocytes, and dystrophic neurites of senile plaques, in hippocampal sections of AD patients." (PMID 28546539, 2017).
steatosis (1 paper, 2023). Increased lipid within the cytoplasm of cells. "Moreover, histological examination further confirmed that the HCC slices showed severe NASH phenotypes, including steatosis and fibrosis, accompanied with elevated FGF9 positive staining by using immunohistochemistry (IHC) analysis." (PMID 37566761, 2023).
testicular cancer (1 paper, 2020). A primary or metastatic malignant neoplasm that affects the testis. "Many studies have shown that FGF9 exerts oncogenic activity and promotes the neoplastic transformation, cell proliferation and invasive/metastatic behavior of lung cancer, gastric cancer, ovarian cancer, prostate cancer and testicular cancer." (PMID 33172093, 2020). "Here, from the microarray analysis of cordycepin-mediated alteration of gene expression levels in testicular cancer cells, the clustering of the microarray data identified that the mRNA level of FGF9 and FGF18 were reduced in 100 μg/mL cordycepin-treated MA-10 cells." (PMID 33172093, 2020). "In summary, cordycepin inhibited FGF9-induced testicular tumor growth by suppressing the ERK1/2, Rb/E2F1, cell cycle pathways, and the expressions of FGFR1-4 proteins, suggesting that cordycepin can be used as a novel anticancer drug for testicular cancers." (PMID 33172093, 2020).
testicular tumor (1 paper, 2020). "In conclusion, our studies revealed the anti-cancer effect of cordycepin on FGF9-induced testicular tumor growth by affecting the expressions of p-ERK1/2, p-Rb, E2F1, cell cycle related proteins, and FGFR1-4 proteins." (PMID 33172093, 2020).
uveal melanoma (1 paper, 2024). A melanoma derived from melanocytes of the uveal tract. "Another study demonstrated that high FGFR expression is associated with poor survival in uveal melanoma patients, and FGF9/FGFR/JNK or ERK signalling cascades are key pathways in regulating hepatic metastasis." (PMID 39001509, 2024).
viral infection (1 paper, 2022). "Taken together, these data indicate that, while 3 days of FGF9 overexpression results in minor increases in select cytokines and chemokines, FGF9 expression appears to sensitize the lung environment to elicit a hyperactive response to viral infection as early as 1 dpi." (PMID 35675358, 2022). "We also observed no ISG15 protein expression by immunofluorescence microscopy in the lungs of FGF9-OE mice following treatment with DOX but without viral infection." (PMID 35675358, 2022).
tumor (70 papers, 2007 to 2026). "The role of FGF9 in the regulation of proliferation of some other cells, especially cartilage-associated tumor cells, is postulated." (PMID 33529250, 2021). "Most of the FGF9‐positive HCC exhibited also elevated levels of FGFR3‐IIIb or FGFR3‐IIIc mRNA causing that 82% of the tumours with overexpression of FGF9 also showed upregulated FGFR3‐IIIb and/or FGFR3‐IIIc." (PMID 32378800, 2020). "In a word, though it wasn’t relevant with poor prognosis in LNCAFs or tumor cells of intestinal-type GC (P > 0.05), but the high FGF9 level was associated with dramatically poor prognosis in diffuse and mixed–type GC (P < 0.01)." (PMID 30646925, 2019). "In primary tumor CAFs, FGF9 expression status was only associated with tumor location (P < 0.05), while in primary tumor cells only associated with age (P < 0.05)." (PMID 30646925, 2019). "Tumor induction in Sftpc-rtTA, Tre-Fgf9-Ires-eGfp mice is often associated with the infiltration of large multinucleated macrophages." (PMID 27056048, 2016). "Immunohistochemical and quantitative RT-PCR analyses showed that Sox7 was underexpressed and was associated with high-grade tumor (P=0.021), increased expressions of β-catenin (P=0.038) and its downstream targets; CyclinD1 (P<0.001) and FGF9 (P<0.001)." (PMID 23295859, 2012). "This indicates that upregulated FGF9 might be associated with tumour infiltration and/or recurrence." (PMID 32378800, 2020). "However, local infiltration, metastatic tumour spread at the time of tumour resection and/or within on average 9 months of follow‐up was associated with enhanced expression of FGF9." (PMID 32378800, 2020). "Interestingly, overexpression of FGF9 causes significant changes in the tumor microenvironment, which includes hyper cellularity and hyper proliferation in the stromal compartment." (PMID 30761180, 2019). "To determine whether treatment with the D11 antibody could cause tumor regression, we induced Sftpc-rtTA, Tre-Fgf9-Ires-eGfp mice with doxycycline for 7 days." (PMID 27056048, 2016). "Deacetylated KLF5 also upregulated CX3CR1 expression in tumor cells, further amplifying FGF9-driven FGFR1 activation." (PMID 41514658, 2025). "Deacetylated KLF5 increased TNF-α secretion by tumor cells, which in turn drove iCAFs toward an earlier, high-FGF9–secreting state, establishing a TNF-α–FGF9 reinforcing loop with Krt4+ cancer cells." (PMID 41514658, 2025). "FGF9 is the member of the fibroblast growth factor family, which is involved in various pathological processes such as angiogenesis, apoptosis, and tumor growth." (PMID 38824534, 2024). "Subcutaneous xenograft tumors with FGF9 overexpression exhibited a more obvious increase in tumor growth than those derived from cells expressing the control vector, as seen by the higher tumor volume and weight." (PMID 37566761, 2023). "For instance, fibroblast growth factor 9 was revealed to normalize tumor blood vessel structure for the vessel hierarchy and vasoreactivity, reducing tumor core hypoxia and VEGF-A expression." (PMID 37908739, 2023). "FGF9 can enhance the tumor-forming ability and resistance to sorafenib in HCC cells, and forced expression of FGF9 is associated with dismal prognosis in HCC patients." (PMID 35837663, 2022). "In adult lungs, FGF9 expression resulted in the rapid development of multiple adenocarcinoma-like tumor nodules." (PMID 34203430, 2021). "FGF9 is secreted mainly by HSCs in normal and cirrhotic livers and acts by the paracrine mechanism to stimulate tumor cells." (PMID 33802841, 2021). "We further observed the effects of cordycepin on FGFR1-4 expressions when MA-10 tumor was exposed to FGF9 in vivo." (PMID 33172093, 2020). "Results showed that FGF9-induced tumor growth in cordycepin-treated mice was significantly smaller than that in a PBS-treated control group." (PMID 33172093, 2020). "Meanwhile, the animal experiment results showed that the IHC expression of FGF9 in FGF9-treated MA-10 tumor tissues was reduced by cordycepin." (PMID 33172093, 2020).
tumor (continued). "In our observations, FGF9 stimulated the expression of FGFR1-4 in MA-10 tumor cells in vitro and in vivo." (PMID 33172093, 2020). "On day 9 after initiation of drug administration, the tumor volumes of the FGF9/PBS group were significantly increased compared to the BSA/PBS and Control/PBS groups, which was consistent with our previous finding in a NOD-SCID model." (PMID 33172093, 2020). "For example, as a tumor suppressor, miR-219a-5p can influence cell proliferation, cell cycle distribution and apoptosis by negatively regulating fibroblast growth factor 9 (FGF9)." (PMID 32122355, 2020). "In both FGF9/cordycepin and Control/cordycepin groups, cordycepin treatment resulted in significantly smaller tumor volume compared to FGF9/PBS and Control/PBS groups, respectively." (PMID 33172093, 2020). "In all, these results indicated that FGF9 offered considerable benefit for the tumor-promoting ability of CAFs, and miR-214 inhibited the tumor-promoting ability of CAFs possibly by directly reducing FGF9 expression." (PMID 30646925, 2019). "In summary, the pro-tumor activities of FGF9 in tumor progression was more pronounced in diffused and mixed–type GC than in intestinal-type GC, despite the high expression of FGF9 in CAFs of intestinal-type GC." (PMID 30646925, 2019). "Our data showed FGF9 exerted anti-apoptotic and pro-migratory effects in vitro and it also accelerated tumor growth in a subcutaneous xenograft model." (PMID 31862949, 2019). "Although the influence of FGF9 expression in tumor cells of primary tumor and lymph node metastatic sites on survival outcome was meaningless, high staining of FGF9 in CAFs of lymph node metastatic sites was indeed associated with poor prognosis." (PMID 30646925, 2019). "What’s more, in lymph node metastatic site CAFs, the expression of FGF9 was related to tumor differentiation and Lauren type." (PMID 30646925, 2019). "The expression of FGF9 was higher in CAFs than that in tumor cells not only in primary tumor but also in lymph node metastatic sites (30.0% vs 11.9%, P < 0.01 and 32.1% vs 12.3%, P < 0.01, respectively)." (PMID 30646925, 2019). "In this regard, FGF9 is exclusively upregulated in fibroblasts in the liver, suggesting its paracrine effect on tumor growth." (PMID 31862949, 2019). "Target genes AXIN2, DKK2 and FGF9, well known for their potential to promote tumor formation and progression in vitro as well as in vivo in CRC, were significantly downregulated in response to SARB46,47." (PMID 31097715, 2019). "In other words, the high expression of FGF9 in gastric CAFs was more important than that in tumor cells themselves." (PMID 30646925, 2019). "Systemically delivered agomiR-4317 reduced tumor growth and inhibited FGF9 and CCND2 protein expression." (PMID 30227870, 2018). "This interaction between miR‐372‐3p and FGF9 in LSCC led to the increase in tumor growth and invasiveness." (PMID 28440022, 2017). "FGF9 belongs to the fibroblast growth factor (FGF) family that participates in a spectrum of biological processes including tumor growth and invasion." (PMID 28440022, 2017). "The direct suppression of FGF9 by miR‐372‐3p and the potential effects of miR‐372‐3p as a tumor facilitator in LSCC have been validated at both experimental and clinical levels." (PMID 28440022, 2017). "Like FGFR3, FGF9 expression has also been identified in several tumor types, including breast, prostate, endometrioid and lung, suggesting an important role in tumorigenesis." (PMID 27056048, 2016). "High FGF9, tumour size, stage, tumour status, node status, and distant metastasis were significantly poor prognostic parameters for OS in GC patients (P < 0.001, P < 0.001, P = 0.008, P < 0.001, P = 0.001, and P = 0.005)." (PMID 27166269, 2016). "Akt and ERK1/2 inhibitors suppressed the phosphorylation of Akt and ERK1/2 in the presence of FGF9 in both mouse primary and tumor Leydig cells." (PMID 24603862, 2014).
tumor (continued). "Our study not only illustrates the relationship between FGF9 and Leydig cell functions but also reveals different properties between normal and tumor Leydig cells." (PMID 24603862, 2014). "Results showed that FGF9 significantly activated steroidogenesis in both mouse primary and tumor Leydig cells (p<0.05)." (PMID 24603862, 2014). "In the present study, we showed that FGF9 activated the phosphorylation of Akt both in mouse primary and tumor Leydig cells, which is consistent with those studies." (PMID 24603862, 2014). "In contrast to Sox7, the upregulated β-catenin was correlated with high-grade tumor (P = 0.045), and two Wnt/β-catenin specific downstream targets; Cyclin D1 (P < 0.001) and FGF9 (P = 0.003)." (PMID 23295859, 2012). "The high expression of FGF9 was maintained between pairs of primary tumors and metastases derived from three patients, indicating that FGF9 activation in the tumor can persist over long periods of time." (PMID 21853123, 2011). "In vivo inhibition of FGF9 resulted in fewer tumour nodules." (PMID 38920685, 2024). "Additionally, FGF9 is identified as a downstream target of miR-187, and targeting FGF9 is crucial for miR-187s tumor-suppressive effects in CC cells." (PMID 39263322, 2024). "Increased FGF9 release in CAFs activates FGFR1 signaling in tumor cells with Klf5KR knockin." (PMID 38781024, 2024). "Moreover, the both total and nuclear β‐catenin protein levels were significantly higher in the FGF9‐overexpressing group than in the control group, and β‐catenin was almost completely localized at the membrane of tumor cells in the control group." (PMID 37566761, 2023). "The DJ-1/Wnt pathway regulates the expression of fibroblast growth factor 9 (FGF9), which more highly expressed in CRC human samples, associated with tumor differentiation, poorer overall survival, and is closely correlated with other EMT markers such as E-cadherin and vimentin expression." (PMID 35563738, 2022). "In addition, immune infiltration assessment revealed that NR0B1 and FGF9 had potential to impact the tumor immune microenvironment." (PMID 35837663, 2022). "Besides that, CXCL12 and fibroblast growth factor 9 (FGF9) produced by CAFs facilitate tumor neovascularization to overcome a hypoxic and acidic TME." (PMID 35967313, 2022). "The P4 peptide, with its antitumor properties, also screened through the phage peptide library, binds to FGF9 to counteract the aggressive phenotype induced by FGF9, including cell migration, invasion, and proliferation in vitro and inhibition of tumor growth in vivo." (PMID 34468956, 2021). "Most of the FGF9‐positive tumours exhibited also elevated FGFR3‐IIIb or FGFR3‐IIIc." (PMID 32378800, 2020). "In addition, a mouse allograft model was performed by intratumoral injection of FGF9 and/or intraperitoneal injection of cordycepin to MA-10-tumor bearing C57BL/6J mice." (PMID 33172093, 2020). "Considering the strong growth inducing effect of FGF9 on preneoplastic hepatocytes, an elevated intrahepatic level of FGF9 in inflamed livers may promote the outgrowth of tumour prestages to frank malignancy via a paracrine mode of action." (PMID 32378800, 2020). "In addition, we show that FGF9 was overexpressed in CRC human specimens and was significantly associated with tumor differentiation." (PMID 32366371, 2020). "This may lead to enhance FGF/FGFR signaling activities which make the way for FGF9 to promote MA-10 tumor growth, since we observed that FGF9 activated the downstream signaling through FGFR2 in MA-10 cells." (PMID 33172093, 2020). "Results showed that the tumor tissue expression of Ki-67 decreased and cleaved caspase-3 increased in FGF9/cordycepin and Control/cordycepin groups, whereas the tumor tissue expression of Ki-67 increased and cleaved as caspase-3 decreased in the FGF9/PBS group." (PMID 33172093, 2020).